PCSK9 (proprotein convertase subtilisin/kexin type 9)
Diseases named in the same sentence as PCSK9 in open-access papers (continued):
Sharing a sentence is not in itself a finding about the gene and the disease.
atherosclerosis (continued). "In recent sophisticated analyses conducted in randomized controlled trials, overexpression of the acquired functional variant proprotein convertase subtilisin/kexin type 9 (PCSK9) induced atherosclerosis in mice." (PMID 36061546, 2022). "We induced atherosclerosis using proprotein convertase subtilisin/kexin-9–adeno-associated virus (Pcsk9-AAV) transfection in transgenic mice overexpressing full-length suPAR (suPARTg) and WT C57BL/6J mice." (PMID 36194491, 2022). "In summary, these studies examined the impact of whole-body Dennd5b deficiency on PCSK9-induced effects on plasma and hepatic lipid concentrations and development of atherosclerosis." (PMID 36243100, 2022). "The inhibition of PCSK9 attenuates atherosclerosis progression and reduces the risk for acute cardiovascular events." (PMID 36232177, 2022). "Recent experimental studies have also implicated PCSK9 in platelet activation, having a key role during atherosclerosis progression." (PMID 35207479, 2022). "Recently, mice manipulated with a proprotein convertase subtilisin/kexin type 9 (PCSK9) gain-of-function mutation have become a popular model to study atherosclerosis." (PMID 35925518, 2022). "With its ability to control the lipid plasma level, the link between PCSK9 and atherosclerosis, a root cause for almost all cardiovascular diseases, was discovered." (PMID 35207479, 2022). "PCSK9 was closely associated with macrophage pyroptosis and the progression of inflammation in atherosclerosis." (PMID 36051574, 2022). "The PCSK9 inhibition attenuates atherosclerosis progression and lowers the risk for acute cardiovascular events." (PMID 36232177, 2022). "LPAR4 inhibition has been demonstrated to decrease the experimental atherosclerosis elicited by adeno-associated virus expressing gain-of-function allele of the PCSK9 D377Y mutation in rats fed a fat-rich diet." (PMID 35269385, 2022). "A growing number of studies have documented the proprotein convertase subtilisin-kexin type 9 (PCSK9) that causes LDL receptor protein degradation as a novel therapeutic target for atherosclerosis prevention and treatment." (PMID 34410548, 2022). "Proprotein Convertase Subtilisin/Kexin type 9 (PCSK9) is a serine protease that plays a major role in the pathophysiology of atherosclerosis and is significantly associated with an increased risk of cardiovascular events." (PMID 36067830, 2022). "In conclusion, our results suggest an association of PCSK9 rs2479409 polymorphism with subclinical atherosclerosis." (PMID 33925815, 2021). "More importantly, PCSK9 has been prompted to be associated with pro-coagulation to aggravate atherosclerosis, apart from regulating plasma LDL-C levels." (PMID 34809656, 2021). "There is gathering evidence that PCSK9 is the cardiovascular risk factor: the higher the PCSK9 levels, the higher the risk of atherosclerosis." (PMID 35024053, 2021). "Our findings are in accordance with current knowledge for the general population, where PCSK9 is associated with atherosclerosis and the progression of atheromatic plaques." (PMID 34692791, 2021). "Single intravenous injection of recombinant adeno-associated viral vector encoding a gain-of-function mutant PCSK9 (AAV-PCSK9) is a rapid and effective method to induce atherosclerosis in mice and a versatile tool for experimental atherosclerosis research." (PMID 35118139, 2021). "The miRNAs we found to be associated with PCSK9 have been all previously reported to play a role in atherosclerosis." (PMID 35071356, 2021).
atherosclerosis (continued). "In this study, our aim is to evaluate the participation of two polymorphisms of the PCSK9 gene as genetic markers for developing subclinical atherosclerosis and cardiometabolic risk factors in asymptomatic individuals." (PMID 33925815, 2021). "On the other hand, high serum levels of PCSK9 have been associated with different vascular diseases such as vasculitis, atherosclerosis, arterial calcification, cerebrovascular, and aortic diseases." (PMID 33925815, 2021). "In summary, PCSK9 and the induction of vascular expression of PCSK9 is causally involved in several steps leading to atherosclerosis, mainly by the downregulation of LDL-Rs and ABCA1 as well as the upregulation of CD36 favoring foam cell formation." (PMID 33364976, 2020). "Aortic root lesions developed in PCSK9 adeno-associated virus mice after the induction of atherosclerosis by a high-fat diet." (PMID 32428130, 2020). "In their cross-sectional study on 330 stable CAD patients, the plasma levels of PCSK9 were positively associated with the platelet count; this indicates that the role of PCSK9 in atherosclerosis involves platelet-associated mechanisms." (PMID 32169071, 2020). "This study mainly focused on the role of exercise on PCSK9 in the liver and the intestine or the application of drugs, such as antibodies, to PCSK9 to reduce the risk of atherosclerosis." (PMID 32325897, 2020). "Studies have investigated the mechanism underlying the PCSK9-monocyte relationship in atherosclerosis." (PMID 32169071, 2020). "In recent years, it has been reported that PCSK9 is linked to atherosclerosis and become an attractive treatment target for CAD." (PMID 33023603, 2020). "Liver transduction with an AAV vector expressing a gain-of-function mutation of PCSK9 under the control of the human α1-antitrypsin promoter induces stable changes in plasma lipid profile and atherosclerosis." (PMID 28291840, 2017). "PCSK9 has emerging therapeutic roles in dyslipidemia-associated diseases, particularly atherosclerosis, and new evidence shows that LVs play a key role in controlling cholesterol efflux from peripheral tissues, such as the atherosclerotic lesion." (PMID 27279328, 2016). "Both OLR1 and PCSK9 are positively linked, where the inhibition of PCSK9 can suppress the development of atherosclerosis by disrupting LOX-1 expression." (PMID 26666837, 2015). "Both OLR1 and PCSK9 genes are associated with atherosclerosis, cardiovascular disease and ischemic stroke." (PMID 26666837, 2015). "Since high levels of these lipoproteins are an important risk factor for atherosclerosis and associated coronary heart disease, finding ways to inhibit PCSK9 has become the focus of much research." (PMID 23580362, 2013). "Myeloid cell‐specific lncAPAT knock‐in mice were generated and injected with recombinant adeno‐associated virus of murine proprotein convertase subtilisin/kexin type 9 to induce atherosclerosis and explore the effects of lncAPAT on inflammation and plaque instability." (PMID 41527512, 2026). "The BRS-induced stenoses in the PCSK9 porcine model may serve as an effective model to investigate natural history of atherosclerosis, and for evaluation of new diagnostic methods, treatment techniques, devices and drugs." (PMID 40131655, 2025).
atherosclerosis (continued). "Studies have shown that lycopene can decrease the expression of PCSK9 in the liver, while citrulline contributes to increased nitric oxide (NO) synthesis, which improves endothelial function and reduces the risk of atherosclerosis." (PMID 40699832, 2025). "Lower expression of PCSK9 could prevent foam cell formation and cholesterol accumulation in the macrophages, and ultimately reduce the risk of atherosclerosis." (PMID 40699832, 2025). "Therefore, the expression of PCSK9 in vascular wall cells is intricately linked to the pathogenesis of atherosclerosis and aneurysms, highlighting its multifaceted role in cardiovascular biology." (PMID 40764605, 2025). "Additionally, the presence of a loss-of-function mutation in the PCSK9 gene or the null mutation R19* in APOC3 was related to a low risk of atherosclerosis." (PMID 40440483, 2025). "Its secretion is intricately linked to inflammatory processes, as PCSK9 has been demonstrated to stimulate pro-inflammatory cytokine production in macrophages and liver cells, thereby establishing a connection between PCSK9 and the inflammatory milieu associated with atherosclerosis." (PMID 40354375, 2025). "Numerous studies have implicated PCSK9 in the induction of oxidative stress, the promotion of chronic inflammation, and the interplay between these processes, particularly in the pathogenesis of atherosclerosis." (PMID 41226572, 2025). "Recent interventional evidence also demonstrates that LDL-C lowering therapies, such as those interfering with PCSK9 mRNA expression, can improve vascular stiffness, suggesting that lipidomic remodeling associated with atherosclerosis may be reversible." (PMID 41515209, 2025). "PCSK9 is significantly associated with inflammation and apoptosis progression in atherosclerosis; therefore, inhibiting its expression may reduce apoptosis and decrease CA-AKI incidence." (PMID 39055658, 2024). "Moreover, a recent systematic review indicates that PCSK9, beyond its role in lipid metabolism, is intricately linked to various diseases including atherosclerosis, central nervous system disorders., sepsis, and chronic renal failure." (PMID 38509591, 2024). "The role of PCSK9 as a predictor of the risk of atherosclerosis is evident from its gain-of-function mutation, which correlates with the occurrence of conditions, such as coronary heart disease (CAD), abdominal aortic aneurysm, peripheral artery disease, and stroke." (PMID 39139638, 2024). "We suggest that therapeutic approaches with PAC1 agonists under real-world clinical conditions could complement statin and PCSK9 (proprotein convertase subtilisin/kexin type 9) therapy of patients at risk of developing atherosclerosis-related pathologies." (PMID 39769009, 2024). "SORT1 augments PCSK9 secretion, and has been implicated in development of atherosclerosis." (PMID 37940228, 2023). "Notably, our results highlight the association between a high-fat diet and PCSK9, providing insights for drug discovery targeting platelet activation in atherosclerosis-induced cardiovascular diseases." (PMID 37892538, 2023). "Similarly, transgenic pigs with the D374Y gain-of-function mutation in the PCSK9 gene are more prone to develop atherosclerosis than WT pigs when fed a high-fat and high-cholesterol diet." (PMID 36970356, 2023). "Besides their significant effects on lipids and ischemic stroke, PCSK9 inhibitors can also mitigate risk factors for ischemic stroke, particularly in the treatment of atherosclerosis." (PMID 38273837, 2023). "This indicates the PCSK9 activation model also exhibits some of the hallmark features of atherosclerosis, allowing for investigation of how PCSK9 might affect these disease characteristics." (PMID 37854060, 2023).
atherosclerosis (continued). "Similarly, fisetin reduced the buildup of lipids in the plaque that causes atherosclerosis by decreasing the activity of proprotein convertase subtilisin/kexin type 9 (PCSK9) and lectin-like oxidized low-density lipoprotein receptor-1 (LOX-1)." (PMID 37174317, 2023). "Therefore, anti-PCSK9 therapy is very beneficial for cardiovascular disease, cerebrovascular disease, and other vascular diseases caused by atherosclerosis." (PMID 38273837, 2023). "Interestingly, fisetin has a clear inhibitory effect on arginase, and also ameliorates atherosclerosis by regulating PCSK9 and LOX-1 in apolipoprotein E deficient mice." (PMID 37047807, 2023). "Therefore, it is needed to deeply understand the roles of PCSK9 in atherosclerosis by unveiling the precise molecular mechanisms underlying it." (PMID 35459215, 2022). "Studies from the last few years have confirmed that PCSK9 accelerates the development of atherosclerosis due to the mechanism associated with increasing plasma concentration of LDL-C, but also by direct influence on the cells which build the arterial walls and atherosclerotic plaques." (PMID 35323699, 2022). "In addition, the observed effect of PCSK9 in the impairment of HDL atheroprotective functions highlights further the importance of PCSK9 inhibition against atherosclerosis and risk of cardiovascular disease." (PMID 36067830, 2022). "Research on PCSK9 and platelet activation is currently underway with the main goal of reducing the risk of advanced cardiovascular events by preventing or slowing down atherosclerosis progression." (PMID 36005422, 2022). "The PCSK9 levels correlated with impaired endothelial vascular health and coronary artery calcium score, suggesting an association between circulating PCSK9 and early, as well as advanced, stages of atherosclerosis in psoriasis." (PMID 35682804, 2022). "The present study has several strengths: first, it analyzes the largest sample so far available investigating the association of PCSK9 with markers of subclinical atherosclerosis; second, it has been carried out in five European countries, thus increasing the results’ generalizability." (PMID 34356905, 2021). "Proprotein convertase subtilisin/kexin 9 (PCSK9) plays an important role in lipid metabolism while available literature regarding its involvement in the pathogenesis of atherosclerosis and in the expression of genes associated with apoptosis and inflammation is constantly increasing." (PMID 34336112, 2021). "Thus, combined with the positive associations between PCSK9 and atherosclerosis or cardiovascular diseases, a positive relationship between PCSK9 and ICCAD was expected." (PMID 34356905, 2021). "An orally available antisense oligonucleotide for PCSK9 has recently demonstrated promise in preclinical studies, and RNA silencing is currently under investigation to target a range of proteins implicated in the pathophysiology of atherosclerosis." (PMID 34468873, 2021). "The Chinese Multi-provincial Cohort Study, which involved 643 participants free of cardiovascular disease at baseline showed that PCSK9 levels are associated with the progression of atherosclerosis, as reflected by the total plaque area, independently of plasma LDL-C concentrations." (PMID 34199468, 2021). "This raises the issue whether PCSK-9 deficiency/inhibition may impact atherosclerosis by decreasing LDL-C concentration as well as by changing the levels of other lipid classes." (PMID 34944757, 2021).
atherosclerosis (continued). "In the present study, we, for the first time, addressed the association of 3 novel circulating atherosclerosis-related lipid measurements including PCSK9, apoC3 and sdLDL-C with current dyslipidemias, to investigate the roles of these markers in determining potential lipid disorders." (PMID 27713142, 2017). "To exclude this possibility, we rendered female whole-body Adam8−/− and wildtype littermate controls prone to atherosclerosis by using a recently developed proprotein convertase subtilisin/kexin type 9 (PCSK9) overexpressing adeno-associated viral vector in combination with WTD feeding." (PMID 28916789, 2017). "Atherosclerosis can be induced by the injection of a gain-of-function mutant of proprotein convertase subtilisin/kexin type 9 (PCSK9)–encoding adeno-associated viral vector (AAVmPCSK9), avoiding the need for knockout mice models, such as low-density lipoprotein receptor deficient mice." (PMID 28291840, 2017). "Plasma PCSK9 levels was positively associated with low-density lipoprotein (LDL) cholesterol (LDL-C) and atherosclerosis, while PCSK9 may also be implicated in the metabolism of lipoprotein subfractions." (PMID 25496400, 2014). "In addition to PCSK9 inhibitors and Lp(a)-targeted RNA-based agents, several other pharmacologic strategies, both established and emerging, are being explored for their ability to modulate shared pathogenic pathways in atherosclerosis and CAVS." (PMID 40943088, 2025). "A multi-target mRNA vaccination, for example, might promote endothelium repair and modulate inflammation in addition to reducing the metabolism of lipids (e.g., by encoding for PCSK9 inhibitors) to provide a holistic therapeutic approach against atherosclerosis." (PMID 39712846, 2024). "For these patients, intensive management of the intracranial significant stenosis caused by atherosclerosis, e.g., high-intensity statins, the proprotein convertase subtilisin/kexin 9 (PCSK9) inhibitor, or even endovascular therapy, may be beneficial for the post-stroke functional recovery." (PMID 37720506, 2023). "Considering that atherosclerosis is the principal cause of ASCVD, the role of proprotein convertase subtilisin/kexin type 9 (PCSK9) cannot be overlooked." (PMID 37620933, 2023). "As an example, in patients with obesity, PCSK9 has a key role on the release of EVs-derived from different atherosclerotic components (i.e., platelets, monocytes/macrophages, endothelium, and neutrophils) and EVs-derived miRNA linked to inflammation and atherosclerosis." (PMID 37378405, 2023). "Thus, for patients with CAD or a high risk of atherosclerosis, statin therapy is commonly prescribed, and some patients may also receive PCSK9 inhibition treatment." (PMID 37620818, 2023). "The development of atherosclerosis risk scores specific for heterozygous FH and the use of subclinical coronary atherosclerosis imaging help with identifying higher-risk individuals who may benefit from further cholesterol lowering with PCSK9 inhibitors." (PMID 36431115, 2022). "The PCSK9 R93C variant may affect the maturation of PCSK9, weaken its proinflammatory and proapoptotic effects, and indirectly delay the onset and progression of atherosclerosis; 3) Hypertension and smoking are risk factors for PMI." (PMID 35480303, 2022). "We evaluated whether administration of tubacin attenuated or reversed the endothelial dysfunction and atherosclerosis induced in mice by a single intraperitoneal injection of adeno-associated viruses encoding liver-target PCSK9 gain-of-function mutant followed by a high fat diet (HFD) for 18 weeks." (PMID 34220539, 2021).